SLC11A1 (solute carrier family 11 member 1)
Diseases named in the same sentence as SLC11A1 in open-access papers (continued):
Sharing a sentence is not in itself a finding about the gene and the disease.
pulmonary TB (11 papers, 2011 to 2023). "It was reported that SLC11A1 polymorphinisms were associated with the presence of cavitary lesions among pulmonary TB patients." (PMID 26626589, 2015). "Several other studies have also pointed out that the SLC11A1 gene not only is associated with TB susceptibility and progression of pulmonary TB but may also play a role in the emergence and development of drug-resistant TB." (PMID 31485302, 2019). "Pronounced tenfold differences between populations were furthermore observed for the missense variant rs17235409 in SLC11A1 that is implicated in treatment failure of patients with pulmonary tuberculosis to isoniazid, rifampicin, pyrazinamide, and ethambutol combination therapy." (PMID 31679053, 2019). "For example, polymorphisms in the gene NRAMP1/SLC11A1 have been associated with pulmonary TB." (PMID 25703549, 2015). "Inversely, research has also been carried out on the 3′ untranslated region (3′UTR) of the SLC11A1 gene in West African, Asian, and South African populations, indicating that the SLC11A1 3′UTR mutation can significantly increase the risk of pulmonary TB." (PMID 31485302, 2019). "Similar associations were observed as well when stratified the analysis on pulmonary TB, which suggests the effect of SLC11A1 polymorphisms might not be influenced by disease types." (PMID 21283567, 2011).
diabetes (9 papers, 2009 to 2025). "In this respect, Slc11a1-deficient female NOD mouse were recently shown to be protected from diabetes." (PMID 26230114, 2015). "Thus, Slc11a1-deficient mice, which are susceptible to intracellular pathogen infections, might also become resistant to diabetes as a consequence of an infection." (PMID 26230114, 2015). "Regrettably, the authors did not specify whether their experiment has been conducted in Specific Pathogen Free facilities, which appears essential to draw a definitive conclusion about the direct role of Slc11a1 in diabetes resistance." (PMID 26230114, 2015). "Although the etiology of Type 1 Diabetes mellitus (T1DM) has not been determined, genetic polymorphism in key genes, including SLC11A1, and association with Mycobacterium avium subspecies paratuberculosis (MAP) have been reported." (PMID 23759115, 2013). "Presence of MAP and SLC11A1 genotypic frequencies in patients with type 1 diabetes mellitus and non-diabetic controls." (PMID 19768110, 2009). "Bivariate and multivariate logistic regression analysis using the presence of MAP and SLC11A1 274C/T genotype to predict diabetes status among patients with type 1 diabetes mellitus and non-diabetic controls." (PMID 19768110, 2009).
salmonellosis (9 papers, 2011 to 2024). Infections with bacteria of the genus salmonella. "Genetic resistance of chickens to systemic salmonellosis seems to be associated with genomic regions carrying the candidate genes NRAMP1 (natural resistance-associated macrophage protein, now SLC11A1), MHC, TLR4 and the quantitative trait locus SAL1." (PMID 34563266, 2021). "Some mouse strains carry a functional allele Slc11a1 (also called NRAMP) coding for a Fe2+/Mn2+/Zn2+transporter, and such mice can successfully control systemic salmonellosis." (PMID 23633950, 2013). "For example, the SLC11A1 gene and the SAL1 locus confer resistance to systemic Salmonellosis, whereas several members of the gallinacin gene family confer resistance to enteric Salmonellosis." (PMID 24912583, 2014).
brucellosis (8 papers, 2010 to 2025). Brucellosis is a bacterial infection that spreads from animals to people via unpasteurized dairy products or by exposure to contaminated animal products or infected animals. "We also estimated the effect of polymorphisms in the coding region of the Slc11a1 gene on resistance or tolerance to brucellosis." (PMID 21637417, 2010). "First, we found a strong relationship between SLC11A1 genotype and brucellosis status." (PMID 32157133, 2020). "The alleles of the goat genes SLC11A1 (formerly NRAMP1), PTPRT, IRF3, and TNF were recently reported by us associated with the absence of Brucella sero-response in Creole crossbreed goats, and variants in the MHC-DRB1 loci were associated with brucellosis susceptibility in Chinese Merino sheep." (PMID 35647101, 2022).
type 1 diabetes (8 papers, 2005 to 2024). "Researchers have shown that UNC13B, PFKFB3, FCN1 and SLC11A1 were diagnostic markers for type 1 diabetes." (PMID 36837510, 2023). "Linkage and congenic strain analyses using the nonobese diabetic (NOD) mouse as a model for human type 1 autoimmune diabetes (T1D) have identified several NOD mouse Idd (insulin dependent diabetes) loci, including Slc11a1 (formerly known as Nramp1)." (PMID 21524304, 2011). "Additionally, SLC11a1 associations have been found with rheumatoid arthritis, visceral leishmaniasis, multiple sclerosis, inflammatory bowel disease, and type 1 diabetes mellitus (T1DM)." (PMID 23056923, 2012). "SLC11A1 allele frequencies for 274 C/T polymorphism differed significantly between T1DM patients and control group, this polymorphism was significantly associated with diabetes type 1, in particular allele 1 and 2 generated a P value of <0.0005." (PMID 19768110, 2009).
typhoid fever (8 papers, 2010 to 2026). A bacterial infectious disorder contracted by consumption of food or drink contaminated with Salmonella typhi. "However, S. enterica serovar Typhimurium, which can cause human diarrhea, causes a systemic infection in mice with pathology and disease progression similar to human typhoid fever in mice defective in Slc11a1 (or NRAMP) encoding a Fe2+/Mn2+/Zn2+transporter." (PMID 25688337, 2014). "Using a 129X1/SvJ (NRAMP+/+ [SLC11A1]) murine model of typhoid chronic infection, we determined that males in this model exhibit increased bacterial burden and mortality in comparison to females (median survival 7 vs 11 days post-infection, respectively)." (PMID 41810958, 2026). "A disease with features reminiscent of typhoid fever can be observed in BALB/c or C57BL/6 mice when inoculated with S. Typhimurium due to a mutation in the SLC11A1 gene, which encodes natural resistance-associated macrophage protein one (Nramp1)." (PMID 25339955, 2014). "Infection of susceptible mouse strains that carry a mutation in the gene encoding for a metal transporter present on the SCV membrane named Nramp1 (Slc11a1), such as CL57/BL6 or BALB/C mice, produces a disease that resembles typhoid fever upon inoculation with S. Typhimurium." (PMID 23055923, 2012). "Neurological disease, while previously characterized in Slc11a1/Nramp1 wild type mice orally infected with S. Typhimurium, is clearly relevant to both HLH and typhoid fever, and may provide a means to clinically monitor response to therapeutic interventions." (PMID 20195482, 2010).
glioma (7 papers, 2022 to 2025). A benign or malignant brain and spinal cord tumor that arises from glial cells (astrocytes, oligodendrocytes, ependymal cells). "To further explore the effect of SLC11A1 in gliomas, we studied the association between its expression and prognosis of gliomas through the analysis of six datasets (n=2390)." (PMID 36531992, 2022). "We used this method to calculate ESTIMATE scores for glioma patients, and the results showed that SLC11A1 was highly positively associated with stromal scores, immune scores and ESTIMATE scores but significantly negatively associated with glioma tumor purity." (PMID 36531992, 2022). "Using the TCGA cohort, we performed subgroup analyses to determine if SLC11A1 is associated with positive prognosis in different subgroups of glioma patients." (PMID 36531992, 2022). "In addition, we revealed the role of SLC11A1 in the development of glioma and assessed the underlying mechanism in immunotherapeutic response." (PMID 36531992, 2022). "Additionally, we explored the mechanisms underlying SLC11A1 in gliomas through gene set enrichment analysis (GSEA)." (PMID 36531992, 2022). "In patients with glioma, SLC11A1 was identified as a stratification indicator for immunotherapy or chemotherapy." (PMID 41007849, 2025). "Further exploration of the GEPIA database revealed that CD47, CTSZ, and SLC11A1 were highly expressed in various cancers, such as glioma, acute myeloid leukemia-like tumors, and pancreatic cancer." (PMID 40129966, 2025). "A retrospective study revealed that SLC11A1 expression predicted the clinical outcome of glioma patients after immunotherapy." (PMID 40356904, 2025). "It is notable that the genes were immune-related genes, according to MSigDB, and SLC11A1 was reported to be associated with the microenvironment in CRC and a similar result was found for CASP6 in gliomas." (PMID 37920710, 2023). "Taken together, our study illustrates that SLC11A1 can serve as a novel indicator for clinical diagnosis, prognostic prediction, and immunotherapeutic response evaluation in glioma patients." (PMID 36531992, 2022). "Next, it was observed that SLC11A1 levels correlate with immune infiltration, resulting in the discovery of possible mechanisms and roles involved in glioma, as well as its potential use for prognosis assessment." (PMID 36531992, 2022). "Clinical characteristics of 1018 glioma patients in the CGGA dataset according to SLC11A1 expression levels." (PMID 36531992, 2022). "Using the multivariate Cox model, SLC11A1 was also an independent determinant [high vs. low HR=2.33, 95% CI (1.92-2.58)] of the outcomes of glioma patients after controlling for grade, IDH status, age, chemotherapy status and recurrence." (PMID 36531992, 2022). "The suggestion that SLC11A1 can be a practical immunotherapeutic target in glioma patients is reasonable." (PMID 36531992, 2022). "According to our current study, SLC11A1 is overexpressed in several kinds of cancer, and especially in gliomas." (PMID 36531992, 2022). "Expression of SLC11A1 increased with progression and predicted unfavorable prognosis for glioma patients." (PMID 36531992, 2022). "Above results showed that SLC11A1 was predominantly correlated with a poor prognosis in patients with human tumors, especially glioma." (PMID 36531992, 2022). "In conclusion, the SLC11A1 expression value was found to be a stable predictor of glioma patient survival." (PMID 36531992, 2022). "To determine the SLC11A1 expression in glioma patients with different tumor grades, we obtained data from a public database and our hospital, and we found that the expression of SLC11A1 was elevated in gliomas tissue with high malignant potential." (PMID 36531992, 2022). "In this study, samples from Shanghai General Hospital and data from TCGA, GEO, CGGA datasets were used to investigate and validate the relationship between SLC11A1 and the progression of glioma." (PMID 36531992, 2022).
glioma (continued). "And based on expression, we found SLC11A1 stratified glioma patients into subgroups with different immune activation statuses." (PMID 36531992, 2022). "We evaluated the predictive value of SLC11A1 on the prognosis of glioma with cox regression analysis." (PMID 36531992, 2022). "This study provided evidence that SLC11A1 was a novel prognostic marker and immunotherapy response indicator for gliomas." (PMID 36531992, 2022). "Studies have shown that the immune-oncology-related gene SLC11A1 is overexpressed in high-grade gliomas and may be a biomarker for predicting the response of high-grade gliomas to temozolomide (TMZ) treatment." (PMID 40129966, 2025). "ImmunCellAI suggested that glioma patients with a high expression levels of SLC11A1 are more inclined to respond to immunotherapy (79%, 406/509) than patients with low SLC11A1 levels (53%, 273/509), and TIDE revealed a similar conclusion (High: 72%, 366/509; Low: 35%, 178/509)." (PMID 36531992, 2022). "Therefore, our study was aimed at discovering how SLC11A1 expression relates to immune infiltration in gliomas and examining the molecular mechanisms by which SLC11A1 plays a role." (PMID 36531992, 2022). "For high grade gliomas, a low expression level of SLC11A1 indicated a better prognosis (p < 0.05)." (PMID 36531992, 2022). "Similarly, in isocitrate dehydrogenase (IDH)-mutant or wild-type glioma patients, longer survival times exist in the low SLC11A1 group (p < 0.05)." (PMID 36531992, 2022). "Anti-SLC11A1 therapy appears to be an appropriate treatment for gliomas." (PMID 36531992, 2022). "Anti-SLC11A1 immunotherapy is a suitable treatment option for glioma, as shown in this study." (PMID 36531992, 2022). "Additionally, we observed that glioma patients with high expression of SLC11A1 were more sensitive to immunotherapy, while glioma patients with low expression of SLC11A1 responded better to temozolomide." (PMID 36531992, 2022). "The expression value of SLC11A1 is a predictable predictor of prognosis for glioma patients." (PMID 36531992, 2022). "We also report that SLC11A1 expression promotes tumor progression and may serve as a biomarker for differentiating molecular subtypes of gliomas." (PMID 36531992, 2022). "Similarly, glioma patients were classified into two groups (high vs. low SLC11A1 expression group) based on the median SLC11A1 level." (PMID 36531992, 2022). "In addition, we also predicted the response to immunotherapy in subgroups of gliomas with high and low expression of SLC11A1, and the results showed that the subgroup with high expression of SLC11A1 had a higher proportion of response to immunotherapy compared to the low expression group." (PMID 36531992, 2022). "In conclusion, the SLC11A1 gene may be a useful indicator of the phenotype of the immune microenvironment within a tumor and may help to predict immunotherapy response in patients with gliomas." (PMID 36531992, 2022). "According to the gene expression, patients were categorized into two subgroups, and the patients with a higher SLC11A1 expression had a lower rate of IDH mutation and higher rates of EGFR and PTEN mutations, and which are considered to indicate a poor prognosis for glioma patients." (PMID 36531992, 2022). "Therefore, we intended to elucidate the evaluable efficacy of SLC11A1 in glioma patients." (PMID 36531992, 2022). "The q-PCR results showed that MSR1 (p < 0.05), IL18 (p < 0.05), SLC11A1 (p < 0.05), and C3AR1 (p < 0.05) were highly expressed in the glioma tissue compared with the normal tissues." (PMID 37370848, 2023). "Glioma patients with wild-type IDH1, mutant EGFR or mutant PTEN showed higher expression of SLC11A1 than those with other phenotypes." (PMID 36531992, 2022). "Therefore, we hypothesized that SLC11A1 may serve as a potential target for glioma treatment." (PMID 36531992, 2022). "However, no study has revealed the function of SLC11A1 in the development of glioma, and the potential molecular mechanism is poorly understood." (PMID 36531992, 2022).
rheumatoid arthritis (7 papers, 2009 to 2025). A chronic, systemic autoimmune disorder characterized by inflammation in the synovial membranes and articular surfaces. "Mutations in SLC11A1 are involved in inflammatory diseases, including Crohn disease and rheumatoid arthritis." (PMID 37370848, 2023).
Autoimmunity (6 papers, 2007 to 2024). The occurrence of an immune reaction against the organism's own cells or tissues. "Interestingly, SLC11A1 (NM_013612.2) has been proposed as an autoimmunity susceptibility gene." (PMID 21637858, 2011). "The transcriptional repression of SLC11A1 gene leads to cell proliferation and survival resulting in cancer and autoimmunity." (PMID 29503661, 2018). "This review discusses the role of the solute carrier family 11 member 1 protein (SLC11A1), formerly NRAMP1 (for natural resistance associated macrophage protein 1), in linking infections, autoimmunity and cancer." (PMID 17378896, 2007). "SLC11A1 is known to link infections, autoimmunity and cancers." (PMID 17378896, 2007). "We then focused on the distinct roles of PTPN22, SLC11A1, and IRF5 in immune regulation and autoimmunity." (PMID 38675400, 2024).
colitis (6 papers, 2008 to 2023). Inflammation of the colon. "Previous studies about the interference of Slc11a1 polymorphism in DSS-induced colitis pointed out the role of IL6 and IFNγ in this disease." (PMID 36792680, 2023). "Here, we investigated the influence of Slc11a1 gene variants on the acute colitis phenotypes induced by DSS using AIRminRR and AIRminSS mouse lines derived from AIRmin-resistant mice as the experimental model." (PMID 36792680, 2023). "The results point to a role of the Slc11a1 S allele in DSS colitis induction in the genetic background of AIRmin mice." (PMID 36792680, 2023). "Together, our results strongly suggest the influence of the Slc11a1 gene on the DSS-induced colitis phenotype." (PMID 36792680, 2023). "Here we investigated the possible modulating effect of the Slc11a1 R and S variants in DSS-induced colitis by using AIRmin mice homozygous for Slc11a1R (AIRminRR) or S (AIRminSS) alleles." (PMID 36792680, 2023). "In addition, SLC11A1 is expressed in macrophages and neutrophils and can regulate macrophage and neutrophil infiltration in arthritis and colitis." (PMID 36755239, 2023).